CACNA1C (calcium voltage-gated channel subunit alpha1 C)
Description:
Pore-forming, alpha-1C subunit of the voltage-gated calcium channel that gives rise to L-type calcium currents. Mediates influx of calcium ions into the cytoplasm, and thereby triggers calcium release from the sarcoplasm (By similarity). Plays an important role in excitation-contraction coupling in the heart. Required for normal heart development and normal regulation of heart rhythm. Required for normal contraction of smooth muscle cells in blood vessels and in the intestine. Essential for normal blood pressure regulation via its role in the contraction of arterial smooth muscle cells. Long-lasting (L-type) calcium channels belong to the 'high-voltage activated' (HVA) group (Probable). [Isoform 12]: Pore-forming, alpha-1C subunit of the voltage-gated calcium channel that gives rise to L-type calcium currents. [Isoform 13]: Pore-forming, alpha-1C subunit of the voltage-gated calcium channel that gives rise to L-type calcium currents. [Isoform 14]: Pore-forming, alpha-1C subunit of the voltage-gated calcium channel that gives rise to L-type calcium currents. [Isoform 15]: Pore-forming, alpha-1C subunit of the voltage-gated calcium channel that gives rise to L-type calcium currents. [Isoform 16]: Pore-forming, alpha-1C subunit of the voltage-gated calcium channel that gives rise to L-type calcium currents. [Isoform 17]: Pore-forming, alpha-1C subunit of the voltage-gated calcium channel that gives rise to L-type calcium currents. [Isoform 18]: Pore-forming, alpha-1C subunit of the voltage-gated calcium channel that gives rise to L-type calcium currents. [Isoform 19]: Pore-forming, alpha-1C subunit of the voltage-gated calcium channel that gives rise to L-type calcium currents. [Isoform 20]: Pore-forming, alpha-1C subunit of the voltage-gated calcium channel that gives rise to L-type calcium currents. [Isoform 21]: Pore-forming, alpha-1C subunit of the voltage-gated calcium channel that gives rise to L-type calcium currents. [Isoform 22]: Pore-forming, alpha-1C subunit of the voltage-gated calcium channel that gives rise to L-type calcium currents. [Isoform 23]: Pore-forming, alpha-1C subunit of the voltage-gated calcium channel that gives rise to L-type calcium currents. [Isoform 24]: Pore-forming, alpha-1C subunit of the voltage-gated calcium channel that gives rise to L-type calcium currents. [Isoform 25]: Pore-forming, alpha-1C subunit of the voltage-gated calcium channel that gives rise to L-type calcium currents. [Isoform 26]: Pore-forming, alpha-1C subunit of the voltage-gated calcium channel that gives rise to L-type calcium currents. [Isoform 27]: Pore-forming, alpha-1C subunit of the voltage-gated calcium channel that gives rise to L-type calcium currents. [Isoform 34]: Pore-forming, alpha-1C subunit of the voltage-gated calcium channel that gives rise to L-type calcium currents. (Microbial infection) Acts as a receptor for Influenzavirus. May play a critical role in allowing virus entry when sialylated and expressed on lung tissues.
Synonyms: CACH2; CACN2; CACNL1A1; CCHL1A1; Cav1.2; TS; LQT8; CACNA1C-IT2; NEDHLSS; TS. LQT8
Tractability: Small molecule: an approved drug acts on it; a structure with a bound ligand is known; a high-quality ligand is known; it belongs to a druggable protein family. Antibody: UniProt places it where antibodies can reach, with high confidence; its Gene Ontology location is reachable by antibodies, with high confidence; UniProt predicts a signal peptide or a membrane-spanning region. PROTAC: its protein half-life has been measured; a small molecule that binds it is known.
Target class: Voltage-gated calcium channel; Ion channel; Voltage-gated ion channel
Safety:
Unwanted effects reported when the protein is acted on. In parentheses: how it was acted on, where the effect was seen, and who reports it.
decreased blood pressure (Bowes et al. (2012): inhibition, cardiovascular system; Lynch et al. (2017): inhibition, acute dosing, central nervous system, cardiovascular)
arrhythmia (inhibition and activation; cardiovascular system, nervous system, gastrointestinal; source: Urban et al. (2012))
constipation (inhibition; cardiovascular system, nervous system, gastrointestinal; source: Urban et al. (2012))
decreased cardiac contractility (inhibition, acute dosing; central nervous system, cardiovascular; source: Lynch et al. (2017))
decreased locomotor activity (activation, acute dosing; central nervous system, cardiovascular; source: Lynch et al. (2017))
decreased PR interval (inhibition; cardiovascular system; source: Bowes et al. (2012))
decreased/increased convulsions (inhibition, acute dosing; central nervous system, cardiovascular; source: Lynch et al. (2017))
dizziness (inhibition; cardiovascular system, nervous system, gastrointestinal; source: Urban et al. (2012))
effect on heart rate (inhibition; cardiovascular system, nervous system, gastrointestinal; source: Urban et al. (2012))
fluid buildup in the legs (inhibition; cardiovascular system, nervous system, gastrointestinal; source: Urban et al. (2012))
headache (inhibition; cardiovascular system, nervous system, gastrointestinal; source: Urban et al. (2012))
hypotension (inhibition; cardiovascular system, nervous system, gastrointestinal; source: Urban et al. (2012))
increased blood pressure (activation, acute dosing; central nervous system, cardiovascular; source: Lynch et al. (2017))
increased cardiac contractility (activation, acute dosing; central nervous system, cardiovascular; source: Lynch et al. (2017))
increased convulsions (activation, acute dosing; central nervous system, cardiovascular; source: Lynch et al. (2017))
increased mortality of heart failure patients (activation; cardiovascular system, nervous system, gastrointestinal; source: Urban et al. (2012))
increased PR interval (inhibition, acute dosing; central nervous system, cardiovascular; source: Lynch et al. (2017))
increased systolic blood pressure (activation; cardiovascular system, nervous system, gastrointestinal; source: Urban et al. (2012))
increases in peripheral vascular resistance (activation; cardiovascular system, nervous system, gastrointestinal; source: Urban et al. (2012))
induction of seizures (activation; cardiovascular system, nervous system, gastrointestinal; source: Urban et al. (2012))
possible shortening of QT interval of ECG (inhibition; cardiovascular system; source: Bowes et al. (2012))
redness in the face (inhibition; cardiovascular system, nervous system, gastrointestinal; source: Urban et al. (2012))
reflex tachycardia (inhibition; cardiovascular system, nervous system, gastrointestinal; source: Urban et al. (2012))
vascular relaxation (inhibition; cardiovascular system; source: Bowes et al. (2012))
adverse events (source: ClinPGx)
alcohol dependence (source: ClinPGx)
suicide (source: ClinPGx)
Gene: Protein-coding gene on chromosome 12 (1,970,772 to 2,697,950, forward strand). Ensembl gene ENSG00000151067.
Subcellular location: Cell membrane; Cell membrane, sarcolemma; Perikaryon; Postsynaptic density membrane; Cell projection, dendrite; Cell membrane, sarcolemma, T-tubule
Subcellular location (Human Protein Atlas): Nucleoplasm; Plasma membrane; Primary cilium
Pathways (Reactome):
Metabolism: Adrenaline,noradrenaline inhibits insulin secretion; Regulation of insulin secretion
Muscle contraction: Phase 0 - rapid depolarisation; Phase 2 - plateau phase
Developmental Biology: NCAM1 interactions
Gene Ontology:
Molecular function: alpha-actinin binding; calmodulin binding; high voltage-gated calcium channel activity; protein binding; voltage-gated calcium channel activity; voltage-gated calcium channel activity involved in AV node cell action potential; voltage-gated calcium channel activity involved in cardiac muscle cell action potential; monoatomic ion channel activity
Biological process: calcium ion transmembrane transport; calcium ion transmembrane transport via high voltage-gated calcium channel; camera-type eye development; cardiac conduction; cardiac muscle cell action potential involved in contraction; embryonic forelimb morphogenesis; heart development; immune system development; membrane depolarization during atrial cardiac muscle cell action potential; membrane depolarization during AV node cell action potential; membrane depolarization during cardiac muscle cell action potential; positive regulation of cytosolic calcium ion concentration; regulation of heart rate by cardiac conduction; regulation of ventricular cardiac muscle cell action potential; calcium ion import across plasma membrane; calcium ion transport into cytosol; cell communication by electrical coupling involved in cardiac conduction; positive regulation of adenylate cyclase activity; positive regulation of muscle contraction; regulation of cardiac muscle contraction by regulation of the release of sequestered calcium ion; monoatomic ion transport; muscle contraction; transmembrane transport
Cellular component: cytoplasm; L-type voltage-gated calcium channel complex; membrane; plasma membrane; postsynaptic density; voltage-gated calcium channel complex; perikaryon; postsynaptic density membrane; Z disc; dendrite; sarcolemma; T-tubule
Genetic constraint (gnomAD): Loss-of-function variants: 23 observed, 174.97 expected, observed/expected ratio (o/e) 0.13, 90% interval 0.094 to 0.19. The upper end of that interval is the gene's LOEUF score, 0.19, which puts it in group 1 of 6, group 1 being the genes least tolerant of losing a copy. Missense variants: 1,494 observed, 2,489 expected, observed/expected ratio (o/e) 0.6, 90% interval 0.57 to 0.63. Synonymous variants: 1,010 observed, 1,013.9 expected, observed/expected ratio (o/e) 1, 90% interval 0.94 to 1.05.
Gene-disease validity (ClinGen):
ClinGen rates the evidence that CACNA1C causes each of these diseases.
Timothy syndrome (autosomal dominant): Definitive.
long QT syndrome (autosomal dominant): Moderate.
Brugada syndrome (autosomal dominant): Disputed. A genetically heterogeneous condition characterized by complete or incomplete right bundle branch block accompanied by ST elevation in leads V1-V3.
short QT syndrome (autosomal dominant): Disputed. A genetic disease of the electrical system of the heart that consists of a constellation of signs and symptoms, consisting of a short QT interval on an EKG (< 300 ms) that does not significantly change with heart rate, tall and peaked T waves, and a structurally normal heart.
Homologues: Orthologues: chimpanzee CACNA1C (99% identical), macaque CACNA1C (99% identical), dog CACNA1C (96% identical), mouse Cacna1c (95% identical), rat Cacna1c (95% identical), rabbit CACNA1C (92% identical), pig CACNA1C (85% identical), guinea pig CACNA1C (84% identical), tropical clawed frog cacna1c (83% identical), zebrafish cacna1c (79% identical). Paralogues in human: CACNA1D (67% identical), CACNA1F (57% identical), CACNA1S (57% identical), CACNA1A (39% identical), CACNA1B (38% identical), CACNA1E (37% identical), CACNA1H (23% identical), CACNA1I (23% identical), CACNA1G (23% identical), SCN2A (23% identical), SCN3A (23% identical), SCN9A (22% identical), and 14 more.
Diseases named in the same sentence as CACNA1C in open-access papers:
CACNA1C is named in the same sentence as 270 diseases in open-access papers, as found by Europe PMC text mining. Sharing a sentence is not in itself a finding about the gene and the disease. The quoted sentences say what the papers report.
Timothy syndrome (182 papers, 2008 to 2025). "First mutations in the CACNA1C gene, which encodes Cav1.2, have been implicated in a multisystem disorder known as Timothy syndrome (TS)." (PMID 40133997, 2025). "Since it’s characterisation in 2004, the spread of variants in CACNA1C associated with Timothy Syndrome has expanded." (PMID 41333400, 2025). "In Timothy Syndrome patients, variants in CACNA1C cause LQT8 in combination with developmental defects, syndactyly, and ASD." (PMID 41274879, 2025). "The CACNA1C gene variants were initially found to be associated with various cardiac arrhythmias, such as Timothy syndrome and Brugada syndrome." (PMID 41177904, 2025). "Mutations in CACNA1C, the gene encoding Cav1.2 voltage-gated calcium channels, are associated with a spectrum of disorders, including Timothy syndrome and other neurodevelopmental and cardiac conditions." (PMID 40133997, 2025). "In the heart, variants in CACNA1C cause several cardiac arrhythmias, including short QT syndrome, Brugada Syndrome, and long QT syndrome type 8 (LQT8)." (PMID 41274879, 2025). "We formalise the language around syndromic presentations linked to CACNA1C variants, reassert and demarcate the classical Timothy Syndrome phenotype, and define a new syndrome, CACNA1C-Related Disorder." (PMID 41333400, 2025). "An example is Timothy syndrome, the complex congenital syndrome caused by CACNA1C mutations, which involves cardiac manifestations such as long QT, along with one or more non-cardiac phenotypes such as skeletal, facial, and neurodevelopmental abnormalities." (PMID 39954672, 2025). "Previous research have demonstrated that pathogenic variants of the CACNA1C gene are historically associated with cardiac arrhythmias, particularly long QT syndrome, Brugada syndrome, and Timothy syndrome." (PMID 41177904, 2025). "With advances in sequencing and the inclusion of CACNA1C in genomic screening, further variants have been identified presenting with incomplete features of Timothy Syndrome or further aligned phenotypes which are inconsistent with the original description." (PMID 41333400, 2025). "Although dental defects as well as gingival hyperplasia have been reported in few previous CACNA1C case descriptions, these clinical characteristics have been found only in association with Timothy syndrome phenotype." (PMID 38790536, 2024). "In Timothy syndrome, mutations in the CACNA1C gene result in a gain-of-function in the calcium channel, leading to an increase in intracellular calcium levels." (PMID 38978817, 2024). "Long QT Syndrome type 8 (LQT8) is a cardiac arrhythmic disorder associated with Timothy Syndrome, stemming from mutations in the CACNA1C gene, particularly the G406R mutation." (PMID 38968219, 2024). "Timothy syndrome is a rare genetic condition that is caused by mutations in the gene encoding the calcium channel protein CACNA1C." (PMID 38978817, 2024). "In general, both CACNA1C gain and loss of function can determine severe neurological and psychiatric symptoms whereas Timothy syndrome is commonly a result of a gain of function." (PMID 38790536, 2024). "In fact, Ca2+ handling is disrupted upon Tmem161 LOF in all contexts studied to date and, crucially, Ca2+ channelopathies can produce both cardiac and neurological disorders: such as in Timothy Syndrome (mutations in CACNA1C (Gene ID ENSG00000151067))." (PMID 37222785, 2023). "The “atypical” variant of Timothy syndrome is characterized by the maximum expression of the CACNA1C gene in exon 8 in the heart and brain (80% CACNA1C mRNA)." (PMID 37958665, 2023). "Timothy syndrome, a rare multisystem disorder induced by mutations in the CACNA1C gene is one of the most penetrant forms of ASD with percentages as high as 60–80%." (PMID 36941261, 2023). "Timothy syndrome is a syndromic form of autism that can be caused by either of three rare de novo mutations in CACNA1C." (PMID 35782381, 2022).
Timothy syndrome (continued). "The paradigm example is Timothy syndrome, in which autistic features are prominent together with a cardiac and skeletal phenotype, caused by a gain-of-function mutation in CACNA1C which acts, at least in part, by altering splicing of the gene." (PMID 36154842, 2022). "For instance, a CACNA1C lesion causing a G406R substitution in the encoded protein was identified in patients with Timothy syndrome; multiple studies have shown that this gain-of-function mutation is associated with prolonged QT intervals, syndactyly, and ASD." (PMID 35220405, 2022). "Variants in CACNA1C coding for a subunit of a voltage-gated calcium channel are associated with Timothy syndrome, next to the LQTS type 8." (PMID 36498454, 2022). "Alteration in the signalling cascade from CaV1.2 to gene regulation in the nucleus is an important cause for autistic behaviour in Timothy syndrome, which is a rare disorder caused by CACNA1C gene mutations and characterized by multi-organ system dysfunctions." (PMID 35013113, 2022). "Gain-of-function mutations in CACNA1C encoding Cav1.2 cause syndromic or non-syndromic type-8 long QT syndrome (LQTS) (sLQT8 or nsLQT8)." (PMID 35862440, 2022). "Further clinical manifestation of CACNA1C gene mutations include “cardiac only” Timothy syndrome (COTS), which is characterized by QTc prolongation and congenital heart defects without extra-cardiac manifestations." (PMID 36523353, 2022). "This current comprehensive systematic review demonstrates that CACNA1C gene mutation associated Timothy syndrome, “cardiac only” Timothy syndrome, and isolated long QT syndrome 8 exhibit major differences regarding clinical manifestations and outcome." (PMID 36523353, 2022). "Gain-of-function mutations in CACNA1C at positions other than exon 8 can cause LQTS with non-Timothy syndrome symptoms." (PMID 35783865, 2022). "Gain-of-function mutations in the calcium voltage-gated channel subunit alpha 1 C (CACNA1C) gene, encoding the CaV1.2 α1-subunit, cause Timothy syndrome (TS), a multisystemic disorder that includes autism spectrum disorders and long QT (LQT) syndrome." (PMID 35897673, 2022). "Meanwhile, a gain-of-function egl-19 mutation, which is equivalent to the Timothy syndrome mutation in CACNA1C, causes defects in axon termination and neuronal polarity in the ALM neuron of C. elegans." (PMID 35782381, 2022). "Cases carrying CACNA1C variants mostly present with Timothy syndrome, which is characterized by ID/GDD, autism, facial abnormalities, heart conditions such as atrioventricular block and patent ductus arteriosus, syndactyly and hypoglycemia." (PMID 33985586, 2021). "Variant V351E (2 residues upstream of the Timothy syndrome mutations in CACNA1C) is located in exactly the same position as mutation V401L, which causes a pronounced type 2 gating change in Cav1.3 and is associated with a severe neurodevelopmental phenotype." (PMID 33746731, 2021). "Timothy Syndrome is caused by a mutation in the CACNA1C gene 25 encoding an L-type voltage-gated calcium channel (LTCs)." (PMID 33390815, 2021). "Both of these egl-19(gof) mutations lead to a G365R amino acid change in EGL-19 that is equivalent to the G402R gain of function mutation in CACNA1C that can cause Timothy syndrome in humans." (PMID 33829152, 2021). "In our previous work, we demonstrated that an egl-19(gof) mutation, which is equivalent to the Timothy syndrome mutation in CACNA1C, can disrupt termination of the PLM axon in C. elegans." (PMID 33829152, 2021). "Two CACNA1C mutations causing Timothy syndrome (G402S and G406R) displayed slowed inactivation but with opposite effects on channel activation." (PMID 34930847, 2021). "Other variants are associated with Timothy syndrome, Brugada syndrome, inborn genetic diseases, and other CACNA1C-related disorders." (PMID 34436362, 2021).